CD4 (CD4 molecule)
Diseases named in the same sentence as CD4 in open-access papers (continued):
Sharing a sentence is not in itself a finding about the gene and the disease.
tumor (continued). "In a subcutaneous tumor-bearing model of lung cancer LLC cells, anlo increased NK cell infiltration, enhanced NK cell and CD4+ T cell to secret more IFN-γ, and increased mature antigen-presenting cells." (PMID 36238642, 2022). "IFN-γ secreted by tumor-reactive CD4+ Th1 cells and CD8+ cytotoxic T cells exhibit pleiotropic effects during the anti-tumor immune response." (PMID 35710296, 2022). "TIME markers, including stromal tumor infiltrating lymphocytes (TILs), CD3, CD4, CD8, and tumor PD-L1 expression, were comprehensively analyzed." (PMID 36528658, 2022). "Furthermore, the transferred cells remained in metastatic lesions and immunohistochemical analysis revealed that all tumor lesions were MHC class II (MHC-II) negative, suggesting that these CD4+ T cells were not responding directly to the MHC-II deficient tumor cells." (PMID 36159781, 2022). "Continuous administration of d-MAPPS increased concentration of CXCL16 in the tumor microenvironment and attracted tumoricidal, perforin, and granzyme-expressing CD8+CTLs, CD4+Th1, and Th17 lymphocytes in the tumors of 4T1+d-MAPPS-treated mice." (PMID 35757015, 2022). "Multiple cohorts of immunocompetent mice were used for oncoimmunology studies, including inflammatory cytokine levels, macrophage, CD4+, and CD8+ cells tumor infiltration at 14 days and 28 days after MST inoculation." (PMID 35966597, 2022). "The counts of CD4+ T cells, CD8+ T cells, and Treg decreased at 48 h after radiotherapy in all experimental groups and had an increased proportion of DC and MDSC in tumor tissues (p < 0.05)." (PMID 35141280, 2022). "In the tumor microenvironment, the ratio of CD8+ T cells to CD4 + FOXP3+ regulatory T cells was significantly elevated and exhausted CD8+ T cells (PD-1+, CTLA-4+, TIM-3+, or LAG-3+ cells) were significantly reduced in the triple combination group." (PMID 35681672, 2022). "For CCA (including both iCCA and eCCA), three studies revealed that CD8+, CD4+ and CD3+ T cells mainly infiltrated outside of the tumor." (PMID 35392957, 2022). "Compared to B-MF, FOB upregulated numbers of CD4+ T cells but decreased frequency of IL10+ CD4+ T cells and GrB+ and Lamp1+ (cytolytic) CD8+ T cells in the tumor, implying that the two cells support cancer independently and without reversal of B-MF to B cells." (PMID 36104343, 2022). "Studies have shown that the ratio of Tregs to CD4+T cells in the tumor and peripheral blood of GBM patients is high, leading to the failure of the remaining CD4+T cells." (PMID 36159398, 2022). "Cytokines produced by DCs also contribute to the production and expansion of activated tumor specific CD8+ and CD4+ T cell populations." (PMID 35418151, 2022). "In tumor samples, we discovered that CD8 T cells are positively related to activated CD4 memory T cells, Follicular helper T cells and Macrophage M1, thus showing that there is cooperation between these cell types." (PMID 35741779, 2022). "Correspondingly, for those MECN clusters mainly occurring in the mixed samples, they were dominated by the same three cell types (i.e., CD8 T, macrophage, and Keratin+ tumor) as MECN cluster 24, except for a rather minor proportion of CD4 T cells." (PMID 36443314, 2022). "The cross-talk between activated DCs and antigen-specific CD4+ T helper and CD8+ cytotoxic T lymphocytes is crucially responsible for the generation of cellular immunity to tumor antigens." (PMID 35757015, 2022). "This suggests that during the early stages of tumor growth, NK cells are the primary source of CD40L or induce its expression on another cell type such as CD4+ T cells, and this is the principal mechanism by which they drive APC maturation." (PMID 36531040, 2022). "A recent study reported, using flow cytometry analysis, the expression, in descending order, of TIGIT, PD-1 and Tim-3 by the TILs (CD4+ and CD8+) of CRC (and that of their ligands by tumor cells)." (PMID 36077799, 2022).
tumor (continued). "The FL microenvironment is composed of tumor-infiltrating CD8+T cells, follicular regulatory and helper CD4+T cells, TAMs and mast cells, follicular dendritic cells, and reticular cells, all involved in the regulation of the prognosis and progression of FL." (PMID 35268349, 2022). "The final step of these immune events is the release of co-stimulatory cytokines by CD4+ T cells and the activation of antigen-specific CD8+ T cells leading to the lymphocyte-mediated destruction of tumour cells." (PMID 36230538, 2022). "In the tumor tissue SAR11675 treatment reduced the predominant population of F4/80+ Ly6Clo and increased CD4+ T cells." (PMID 35681695, 2022). "To confirm that T cells in LAIT‐treated tumours were activated, we performed cell trajectory inference (CTI) analysis, using R package Monocle2,46 on CD8+ and CD4+ T cells." (PMID 35808806, 2022). "DC-originated cognate memory CD4+ T cells can influence the expansion, transportation, and differentiation of secondary CD8+ T cells, thereby significantly increasing control on tumor growth." (PMID 35912206, 2022). "In TILs from the primary tumor site in five patients with OSCC, 4.19% of CD8+ T-cells and 11.4% of CD4+ T-cells expressed CCR4." (PMID 36522365, 2022). "T lymphocytes are mainly divided into two subsets, CD4+ T cells and CD8+ T cells, and the specific immune responses they mediate are an important part of anti-tumor cellular immunity and are closely related to tumor development and prognosis." (PMID 36439168, 2022). "The authors confirmed that the DC–RCC hybrid stimulated CD4+ and CD8+ T cells to produce IFN-γ, and vaccination of patients with the DC–RCC hybrid resulted in decreased tumor size." (PMID 35806328, 2022). "Similar to the murine system, NDV enhanced CD8+ T cell activation, and that of CD4+ T cells, per their increased proliferation and IFN-γ production, and increased sensitivity of tumor cells to contact-mediated T cell killing." (PMID 36418317, 2022). "To further characterize the cytotoxicity of dominant cells, we sorted CD4+ and CD8+ T cells from the spleen of tumor-free mice on day 56 and examined the cytotoxic capacity of these two cell types with flow cytometry." (PMID 36365247, 2022). "But at the same time, we found that the high expression of WTAP also promoted the high infiltration of some immune cells that are thought to mediate the anti-tumor response, such as CD8+T cell and CD4+T cell." (PMID 36171885, 2022). "These CD4+ T cells express molecules such as CD40L, CD80, and CD54, which can promote tumor growth and disease progression through the activation of important pathways such as NF-kB." (PMID 35267668, 2022). "PD-L1 is expressed on antigen-presenting cells and neoplastic and tumor-infiltrating immune cells; on the other hand, PD-1 is expressed on CD8+ and CD4+ T-cells, B-cells, and natural killer (NK) cells." (PMID 35743435, 2022). "These key risk–related molecular models can activate not only some innate immune cells (NK cells) but also tumor-specific T cells (CD4+ and CD8+ T cells) and recruit APCs into the tumor to initiate an immune response." (PMID 35860357, 2022). "Various research investigation indicates that abnormal m6A modification occurs in most immune cells, including dendritic cells, regulatory T cells, macrophages, CD4+ T cells, and CD8+ T cells, and results in tumor escape or immune disorder." (PMID 35372339, 2022). "All these results indicated that Th1-dominant CD4+ T cells induced by cryo-thermal therapy regulated the expression of IFN-γ in CD8+ T and NK cells and enhanced their cytotoxicity against tumor cells." (PMID 35874660, 2022). "An increase in GrB+ and IFNγ+TNFα+ CD4+ T cells with fewer central memory T cells and surprisingly fewer IFNγTNFα+ CD8+ T cells in tumor, with a decreased presence of myeloid, notably HLA-DRlo cells, correlated with smaller tumors." (PMID 36419897, 2022).
tumor (continued). "The results indicated that the expression of CD68 was positively related to the abundance of B cells, CD4+ and CD8+ T cells, dendritic cells, macrophages, and neutrophils in many tumor types." (PMID 35550532, 2022). "CD8+ Teff (CTL) are immune anti-tumor effector cells whereas regulatory T cells (Treg, CD25+CD4+FoxP3+) can suppress this cytotoxic T-cell function." (PMID 36009387, 2022). "It has been proposed that CD4+ T-helper cells can aid the survival of infused CD8+ T cells, induce tumor cell senescence through derived cytokines, and even differentiate into cytolytic effectors 7-9." (PMID 35154479, 2022). "The activated CD4+ and CD8+ CTL play an antitumor role by inhibiting the division and proliferation of tumor cells in vivo." (PMID 36355531, 2022). "Strong tumor infiltration with CD3+, CD4+, CD8+, and CD20+ immune cells correlated significantly with improved OS." (PMID 36010989, 2022). "According to previous researches, the high level of tumor-infiltrating lymphocytes (TIL), such as NK cells, CD8+ T cells, CD4+ T cells, and activated B cells, was generally relevant to durable response to immunotherapy and better prognosis." (PMID 36138406, 2022). "scRNA-seq and spatial transcriptomics have also been applied to a recently developed mouse model of human neuroblastoma, revealing that the spatial relationship of CD4+ and CCR2+ macrophages play a pro-tumor role via the arginine metabolic pathway." (PMID 36376874, 2022). "Immunofluorescence staining was used to assess the proliferation of CD4+ HTLs and CD8+ CTLs in order to further illustrate the anti-tumor immune response of the self-driven probiotic CRISPR/Cas9 delivery nanosystem strategy." (PMID 36550159, 2022). "CD3+ cells are considered the major immune effectors in cellular immune responses, consisting of CD4+ T helper cells and CD8+ cytotoxic T cells, which cooperate to mediate local anti-tumor immunity." (PMID 35227234, 2022). "Individuals who were free from tumor recurrence after 6 months had higher proportions of CD8+ T cells and higher ratios of CD8+/CD4+ before the induction treatment." (PMID 36387134, 2022). "The efficacy of Lm-LLO-CD105A was associated with increased infiltration of polyfunctional (i.e, IFN-γ, TNF-α, and IL-2 producing) CD8+ and CD4+ T cells and reduction in immunosuppression within the TME, and reduced tumor vascularization." (PMID 36439126, 2022). "These vaccines were shown to elicit robust anti-tumor immune responses through activation of tumor antigen-specific CD8+ and CD4+ T cells." (PMID 36351947, 2022). "Metastasis also had lower infiltration of tumour-eliminating immune cells, including CD8 + T cells, CD4 + memory resting T cells, and plasma cells." (PMID 35904677, 2022). "A gene model with five immune protein markers (CD4 on TILs, CD3 on TILs, Gal-9 on tumor cells, PD-1 on TILs, and PD-L1 on tumor cells) was with the all the frequencies of 2000." (PMID 36263183, 2022). "TCL-mediated cancer immunotherapy has been shown to involve the activation of tumor-specific CD8+ and CD4+ T cells via a vast array of immunogenic epitopes." (PMID 35890254, 2022). "TILs are one of the major components in the tumor microenvironment, including different proportions of CD3+CD4+ (helper T) cells and CD3+CD8+ (cytotoxic T) cells." (PMID 36102418, 2022). "After treatment with aPNs, not only the number of neutrophils, CD8+, CD4+ T cells, and B cells increased, but also IL-12, TNF-α, and IFN-γ levels elevated significantly in tumor tissues." (PMID 36034656, 2022). "Mice with cDC1-specific inactivation of CD40 failed to reject tumors normally rejected by WT mice, in a system where tumor rejection requires both CD8 priming and CD4 help." (PMID 35543702, 2022). "The enrichment of tumor-infiltrating immune cells showed an increase of DCs, CD8 + T cells, CD4 + T cells and NK cell in patients with better prognosis." (PMID 36072337, 2022).
tumor (continued). "A phase II trial analyzing neoadjuvant PROSTVAC in patients awaiting RP showed an increase in CD4+ and CD8+ T cell infiltration of the tumor, as well as a peripheral immune response to neoantigens in 13 out of the 25 patients." (PMID 36139368, 2022). "It is also well acknowledged that modulation of the intra-tumor T cell equilibrium toward a CD4+Th1 response is critical to promote cytotoxic CD8+ T cell functional activity and an effective anti-tumor response." (PMID 36428727, 2022). "It is also reported that CD4+ and CD8+ T cells are both necessary for the optimal anti-tumor responses." (PMID 36118042, 2022). "Substitution of NF-αCTLA4 for αCTLA4 significantly reduced the percentage of CD4+/CD45+ and increased CD8+/CD45+ in the primary tumor." (PMID 36405757, 2022). "Next, we compared different immune subsets (CD3, CD4+, CD8+ T cells, and NK cells) between the tumor and adjacent healthy kidney tissue." (PMID 35003893, 2022). "High Treg prevalence in CD4+ T cells and low CD8+ T cell density are independently correlated with advanced tumour stages, high tumour grade, and distant metastasis." (PMID 36077801, 2022). "In the spleens of KPC4580P tumor bearing mice, the TIGIT+ CD4 T cells were mostly found in the antigen-experienced CD11ahiCD49dhi cell population and did not produce IFN-γ after in vitro re-stimulation." (PMID 36569934, 2022). "Three days after tumor injection, mice were intravenously injected with a course of 10x106 vector control NK92 cells, CD4 CAR NK92 cells, or CD4-IL15/IL15sushi CAR NK92 cells." (PMID 36172388, 2022). "NETs enhance differentiation of regulatory T cells by promoting mitochondrial oxidative phosphorylation in naive CD4+ T cells via TLR4, amplifying tumor burden." (PMID 35574410, 2022). "This suggests increased numbers of pro-inflammatory Th1 and Th17 CD4+ T cells which can, in addition to augmenting anti-tumor cytotoxic responses by CD8+ T cells, mediate direct anti-tumor activity by the production of cytokines." (PMID 35507536, 2022). "Immune cells such as dendritic cells, macrophages, and CD4+ and CD8+ T cells can potentially play a role in antitumor immunity in the tumor milieu." (PMID 36232335, 2022). "In contrast, an increased percentage of CD4+ and CD8+ T cells infiltrating the tumor tissue after administration of these vaccines was noted." (PMID 35372586, 2022). "IRE + STING: Reduced the tumor volume, induced a M1/M2 macrophage balance towards the anti-tumor M1 phenotype, and increased the tumor infiltration of CD8+ and CD4+ T cells compared to IRE or STING alone." (PMID 35740542, 2022). "Once regarded as an experimental artefact, cytotoxic CD4+ T cells (CD4 CTL) are presently recognized as a biologically relevant T cell subset with important functions in anti-viral, anti-tumor, and autoimmune responses." (PMID 35903098, 2022). "In other words, contrasting to MC38/Hepa1-6, the roles of CD4+ and CD8+ in this tumor remains inconclusive at this stage." (PMID 35228603, 2022). "4T1 tumors from FGFRi-treated mice had significantly increased CD8+ T cells (cluster 1) and CD4+ T cells (cluster 2), and decreased myeloid-derived suppressor cells (MDSC) (cluster 7), suggesting enhanced anti-tumor immunity." (PMID 35832090, 2022). "There were more anti-tumor immune cells in C2 such as CD8+ T cells, activated CD4+ T memory cells, activated NK cells, and M1 macrophages." (PMID 36211436, 2022). "More recently, GM-CSF was shown to drive anti-tumor CD4+ and CD8+ T cell immune responses by activating IRF-5 in eosinophils in the tumor microenvironment." (PMID 35865534, 2022).
tumor (continued). "After binding to 4-1BB on tumor cells, NK cells had an increased CD73 surface expression, which triggered STAT3 activation and TGF-β/IL-10 secretion correlating with reduced CD4+ T cells proliferation and IFNγ production." (PMID 35769460, 2022). "Consistently, memory T lymphocytes were detected to reduce in theca layer of PCOS, and CD4(+) memory T cells were proved to proliferate and secrete INF-γ preventing tumor growth." (PMID 36060967, 2022). "An immunosuppressive environment of reduced CD4- and CD8+ T cells promotes tumor invasion, tumor growth and tumor escape, thereby aiding the development of immune checkpoint inhibitor resistance." (PMID 35205798, 2022). "More recently, transduction of primary human CD4+ T lymphocytes with the NPM-ALK transgene has led to in vitro transformation of the cells and in vivo tumor formation." (PMID 35246138, 2022). "Blocking galectin-9 can lead to reversal of immunosuppression, activation of CD4+ and CD8+ T cell effect and enhancement of anti-tumor effect, thus enhancing the killing effect of immune cells on PDAC cells and inhibiting growth and metastasis." (PMID 35965504, 2022). "Through this study, we investigated the expression of PD-1 and CD39 on CD4+ and CD8+cells infiltrating tumor tissue compared to their counterparts in peripheral blood." (PMID 35051220, 2022). "The IHC staining of CD8+ T cells, CD4+T cells, NK1.1+ NK cells, CD68+TAM, FOXP3+Treg cells and CD11C+ DCs in the tumor tissues also showed a similar trend." (PMID 35525959, 2022). "A comprehensive correlation matrix was created to seek the correlates of DTICs, including CD3+, CD4+, CD8+, CD68+, and FOXP3+ cells in central-tumor and invasive-margin areas." (PMID 35443723, 2022). "More pCR was seen in patients where pretreatment biopsies showed CD8 = CD3, CD8 ≥ CD4, positive IL33 tumor cell scores, and IL33 in immune cells < tumor cells." (PMID 35566403, 2022). "Treatment of tumor-bearing mice with oleclumab slowed tumor growth and enhanced CD8+ and CD4+ T cell infiltration in colon cancer models." (PMID 36077755, 2022). "In this study, the level of CD4+ T cells in PBMC and in tumor between different groups was determined using flow cytometry (FCM)." (PMID 35578660, 2022). "The representative H&E and immunohistochemical staining images demonstrated that CD3, CD4 and CD8 expression was rarely seen and moreover were generally scattered throughout the tumor or normal tissues, but occasionally appeared in clusters in PTC-WO." (PMID 35720279, 2022). "Tumor-infiltrating lymphocytes (TILs) are found in 75% CW (and approximately 86% in metastases), including CD8+ T lymphocytes, CD4+ T lymphocytes, CD20+ B lymphocytes, and CD117+ mast cells." (PMID 36297616, 2022). "The expression of PITX1 was significantly correlation with tumor-infiltrating CD8+ T cells (Rho = −0.15, p = 8.56e−04), CD4+ T cells (Rho = 0.166, p = 2.22e−04), macrophages (Rho = −0.248, p = 2.36e−08), and DCs (Rho = −0.207, p = 3.83e−06)." (PMID 36204311, 2022). "Tumors of diverse types have been found to express TIM-3, including CD4+ and CD8+ tumor-infiltrating lymphocytes in BLCA, SKCM, and KIRC." (PMID 36081997, 2022). "Flow cytometry analyses showed that the proportion of intra-tumor CD3+, CD4+, and CD8+ T cells in CD45+ cells was lower in uIRI-Can than in Sham-Can." (PMID 36470862, 2022). "Consistently, microbial ablation in mice resulted in increased infiltration of Th1-polarized CD4+ and CD8+ T cells, decreased accumulation of MDSCs, and a TAM reprogrammed to a tumor-protective M1-like phenotype." (PMID 36408139, 2022). "The biggest difference was observed for B lymphocytes, where the expression levels in the tumor samples were over five times higher (5.41 times), over two times higher for CD8+ T cells (2.34 times), and almost two times higher for CD4+ T cells (1.79 times)." (PMID 35158748, 2022).